APOE (apolipoprotein E)
Diseases named in the same sentence as APOE in open-access papers (continued):
Sharing a sentence is not in itself a finding about the gene and the disease.
tauopathy (continued). "The convergence of ApoE-driven lipid metabolism with the failure of lysosomal degradation helps explain the accelerated lysosomal stress in APOE4 carriers, earlier deposition of lipofuscin in a mouse model of tauopathy, and increased vulnerability of specific neuronal populations." (PMID 41387918, 2025). "However, contrarily, the results of a study performed on a large group of patients with PSP (n = 202) and CBD (n = 41) did not reveal a correlation between increased levels of ApoE and these tauopathies." (PMID 39202319, 2024). "Since the tauopathy negative group (without both AD-tau or AGD-tau) also showed associations among Aβ, apoE, and pTau181, their interactions are likely diminished through unknown mechanisms in AGD-tau positive cases." (PMID 38336940, 2024). "Overall, there is a lack of consensus regarding the effect of APOE isoform on tauopathy in model systems and in human AD brain, although there are indications that APOE4 may preferentially influence regions involved in the initial spread of tau." (PMID 37600228, 2023). "Multiple factors including APOE isoforms, tau conformational strains and the epichaperone system might therefore modulate tau transmission via LRP1, partially explaining the diverse neuropathologies and clinical syndromes found in different tauopathies." (PMID 33424736, 2020). "Finally, APOE ε2 has been shown to increase primary tauopathy pathology when Aβ is not present and thus, effects of APOE may be dependent on the presence of Aβ pathology." (PMID 33815065, 2021). "There continues to be strong interest in whether a mechanistic relationship exists between APOE and brain parenchymal tau that is independent of amyloid, as has been suggested by analyses of primary tauopathies and selected studies using cellular and animal model systems." (PMID 33426524, 2020). "A less likely explanation might be contamination of non-AD tauopathies in APOE ε4 non-carriers." (PMID 31866851, 2019). "Further, we did not observe neurodegeneration in any of the APOE genotypes at 6 months of age, which is consistent with the previously reported phenotypes using AAV-tau as tauopathy mouse model." (PMID 30348994, 2018).
COVID-19 (131 papers, 2020 to 2026). A disease caused by infection with severe acute respiratory syndrome coronavirus 2. "Another important gene associated with COVID-19 is APOE encoding apolipoprotein E. This gene not only influences lipoprotein function but also plays a crucial role in the inflammatory responses of macrophages." (PMID 40722786, 2025). "Whereas, rs429358, which is linked to APOE, has been previously reported as shared genetic between COVID-19 and AD." (PMID 40580451, 2025). "The presence of the ApoE ε4 allele in some individuals is another link between COVID-19 and Alzheimer’s." (PMID 39201402, 2024). "Consistent with this pattern, the APOE genotype was associated with survival in patients infected with COVID-19 and part of the UK Biobank; E4 homozygote carriers showed poorer survival than E3 homozygote carriers." (PMID 39660133, 2024). "Clinically, the correlation between APOE ε4 carriers and COVID-19 patients suggests that APOE ε4 is associated with increased susceptibility to SARS-CoV-2 infection and elevated serum inflammatory factors." (PMID 37962454, 2024). "In the UK Biobank community cohort study, the risk of COVID-19-related hospitalization was more than two-fold higher among APOE ε4/ε4 homozygotes compared to ε3/ε3 homozygotes." (PMID 36717892, 2023). "Those integrate data conclude that the ε4 allele of ApoE gene is not only associated with risk but also the severity of COVID-19." (PMID 36759834, 2023). "For example, the APOE ε4 allele has been associated with an increased risk of severe COVID-19 as well as post-COVID mental fatigue." (PMID 36901217, 2023). "Prospective studies are also warranted to evaluate APOE variants as a biomarker for identifying patients at high risk of poor outcomes of COVID-19." (PMID 36717892, 2023). "In the present study, a meta-analysis was conducted and the integrated results clarified that ε4 allele of ApoE gene is associated with the increased risk and severity of COVID-19." (PMID 36759834, 2023). "The pooled results showed that ApoE gene polymorphism (ε4 carrier genotypes VS non-ε4 carrier genotypes) is associated with a high risk of COVID-19 (P = 0.0003, OR = 1.44, 95% CI 1.18–1.76)." (PMID 36759834, 2023). "A meta-analysis was conducted to clarify the association between ApoE polymorphism and the risk and severity of COVID-19." (PMID 36759834, 2023). "A total of 2325 COVID-19 cases and 644063 controls from six case–control studies concentrating on the association between ApoE gene polymorphism and the incidence of COVID-19 were included." (PMID 36759834, 2023). "The latest report by Ostendorf and colleagues further confirmed the influence of APOE variants on COVID-19 outcomes in an established SARS-CoV-2-infected APOE knock-in mouse model." (PMID 36717892, 2023). "Direct comparison of two GWASs allowed to identify locus chr19:44,744,108–46,102,697 containing APOE gene as a possible risk region for both COVID-19 and AD." (PMID 37927339, 2023). "Compared to the two other isoforms, APOE4 is genetically associated with reduced apoE levels, which increases the risk of coronavirus infection and disease progression, and this reduction is consistently associated with severe COVID-19." (PMID 36089575, 2022). "ApoE is one of the highly co-expressed genes in type II alveolar cells in the lungs, and the ApoE e4e4 homozygous genotype was reported to increase the risk of severe COVID-19." (PMID 36204639, 2022). "A cohort study showed that the risk of hospitalization due to COVID-19 was 2.3- to 4.0-fold higher among homozygous for APOE ε4 than among patients with the common APOE ε3/ε3 genotype." (PMID 35954930, 2022). "The ApoE ε4 genotype was investigated in the UK Biobank Cohort, being associated with COVID-19 severity and mortality." (PMID 35793369, 2022). "APOE gene polymorphisms have been reported to be associated with susceptibility or severity of COVID-19 in British, Czech, Spanish, Finnish and Kurdish population." (PMID 36531218, 2022).
COVID-19 (continued). "The CD4+ macrophages in COVID-19 also expressed several other markers of monocyte-derived alveolar macrophages, including the APOE transcript and genes encoding the complement component C1Q." (PMID 35446789, 2022). "To conclude, we previously showed that APOE e4 genotypes are associated with increased COVID-19 severity." (PMID 34171089, 2022). "As far as we know, no publications have evaluated cognitive manifestations after COVID-19 and correlated them with APOE polymorphisms." (PMID 36046159, 2022). "As APOE3 and APOE4 differentially affect SARS-CoV-2 infectivity, we investigated the association of APOE genotype with COVID-19 incidence." (PMID 35915083, 2022). "Consistent with above findings, we revealed an association of APOE variant rs429358 with susceptibility to COVID-19 in Chinese population." (PMID 36531218, 2022). "The APOE ε4 allele was a risk factor for severe COVID-19 and post-COVID mental fatigue, whereas protective effect of ε2 allele against SARS-CoV-2 infection was shown." (PMID 36292001, 2022). "Several studies have been performed to find a possible link between APOE polymorphism and the severity of COVID-19 symptoms, and it has recently joined the network of APOE e4-related diseases." (PMID 35931737, 2022). "Studies have shown that coronavirus disease 2019 (COVID-19) and AD share common risk such as age, sex, hypertension, diabetes, APOE 4ε, links with the ACE2 receptor, increased oxidative stress, and obesity." (PMID 36291338, 2022). "Regarding COVID-19 severity, the HLA-A*33, ACE1 Ins, and TMPRSS2 rs12329760T alleles were associated with protection against severe forms, while the HLA-B*38, HLA-C*6, and ApoE rs429358C alleles were associated with risk for severe forms of COVID-19." (PMID 35793369, 2022). "More severe COVID-19 manifestations in patients have been correlated with the APOE-4 allele of the apolipoprotein E (APOE) gene." (PMID 36046159, 2022). "The ε4 allele of APOE, the strongest genetic risk factor for AD, has been found to be linked to increased risk of infection and mortality due to COVID-19, although the biological mechanisms involved remain to be discovered." (PMID 35409141, 2022). "Among hospitalized patients with severe pneumonia, COVID-19 is independently associated with higher NEFAs (mainly linoleic and arachidonic acids) and lower apolipoprotein E and HDL concentrations." (PMID 34031519, 2021). "This study investigated frequencies distribution of alleles that alter the ApoE expression in lung tissues to trace a profile of these variants and associate them to COVID-19 clinical outcomes." (PMID 34179542, 2021). "Noteworthily, AD and COVID-19 share several risk factors and comorbidities, such as age, gender, hypertension, diabetes and APOE ε4 expression." (PMID 33673697, 2021). "The present study indicates a potential genetic contribution of APOE expression-modifying variants in assess poor prognosis of COVID-19, such as severity and mortality outcomes." (PMID 34179542, 2021). "To assess the association between APOE and COVID-19, we used data from FinnGen release 7, which integrates genome-wide genotype data of over 300,000 subjects with phenotype data derived from national registries." (PMID 34949230, 2021). "The UK study performed in451,367 patients, those with the ApoE e4e4 gene variant are 2.3 to 4 times more prone tobe infected with and test positive for COVID-19 than others." (PMID 34222864, 2021). "In conclusion, COVID-19 was independently associated with high concentrations of polyunsaturated NEFAs and low concentrations of apolipoprotein E and HDL." (PMID 34031519, 2021). "Here we studied the genetic association between APOE and COVID-19 in Finnish biobank, autopsy and prospective clinical cohort datasets." (PMID 34949230, 2021). "The present study indicates a potential genetic contribution of APOE expression-modifying variants in modulating the prognosis of COVID-19." (PMID 34179542, 2021).
COVID-19 (continued). "The objective of this study is to investigate the frequency distribution of alleles responsible for altering gene expression of APOE in lung tissues to trace a profile of these variants and link them to poor clinical outcomes of COVID-19 patients worldwide." (PMID 34179542, 2021). "More research is needed to determine the real impact of APOE alleles in COVID-19 morbid-mortality and host resistance to SARS-CoV-2 infection." (PMID 34945790, 2021). "We, therefore, aimed to test associations between ApoE e4 alleles and COVID-19 severity, using the UKB data." (PMID 32451547, 2020). "In conclusion, ApoE e4e4 genotype is associated with COVID-19 test positivity at genome-wide significance (ie, p < 5 × 10−8) in UKB, using data covering a longer period than previously reported." (PMID 32623451, 2020). "In the second study of COVID-19 mortality, authors reported an association between APOE*E4/*E4 homozygous status and increased risks of mortality with test-confirmed COVID-19 when compared to APOE*E3/*E3 homozygotes." (PMID 32803253, 2020). "The p values of the observed association between APOE*E4/*E4 homozygotes and COVID-19 positivity indeed ranged from 1.23 × 10−9 to 2.10 × 10−7." (PMID 32803253, 2020). "The precise biological mechanisms linking ApoE variants to COVID-19 severity require further investigation." (PMID 33414783, 2020). "Is APOE ε4, an established risk factor for AD and vascular dysfunction, also a risk factor for COVID-19?" (PMID 33380345, 2020). "We also observed that COVID-19 patients showed the down-regulation of apolipoprotein A-IV (APOA4) and apolipoprotein E in COVID-19 patients, possibly associated with macrophage function." (PMID 33203833, 2020). "More data are needed on ApoE and COVID-19 associations in other ancestry groups, as numbers of UKB participants of such groups are unfortunately too small for this analysis." (PMID 32623451, 2020). "We have read with great interest both papers which described an association between the epsilon alleles of the APOE gene and the severity and the mortality rate of COVID-19." (PMID 32803253, 2020). "From the number of genes with altered expression induced by statins, we focused on those reported to be involved in a complicated course of COVID-19, including APOE and ACE2, genes encoding proteins involved in innate antiviral immunity and respiratory failure genes." (PMID 40722786, 2025). "Furthermore, we conducted a multivariate logistic regression with demographic covariates (age, sex, and the APOE genotypes) to determine any confounding effects on the association between PRSs of COVID-19 and AD." (PMID 39764106, 2024). "Apolipoprotein E4 (ApoE4) has been associated with COVID-19 and with severe COVID-19." (PMID 36899824, 2023). "In addition, recent studies have shown that the apolipoprotein E ε4 allele (APOE4) is directly linked to similar genetic factors implicated in COVID-19 and AD." (PMID 37106622, 2023). "In particular, APOE-ε4 may promote the susceptibility of viral infection and cerebrovascular disease during COVID-19." (PMID 37238686, 2023). "Recent studies also reported that APOE has an impact on COVID-19 susceptibility and severity." (PMID 36717892, 2023). "ApoE gene polymorphism (ε4 carrier genotypes VS non-ε4 carrier genotypes) is associated with the increased risk (P = 0.0003, OR = 1.44, 95% CI 1.18–1.76) and progression (P < 0.00001, OR = 1.85, 95% CI 1.50–2.28) of COVID-19." (PMID 36759834, 2023). "In addition to ACE2, TMPRSS2 and TLRs, other genetic elements like Apolipoprotein E (APOE) have been reported to increase risk of severe COVID-19." (PMID 35956081, 2022). "Interestingly, individuals homozygous for ApoE e4 (rs429358) have twice the risk of severe COVID-19 compared to the most common ApoE e3e3 genotype." (PMID 35618891, 2022).
COVID-19 (continued). "In addition, the missense variant rs429358 in exon of APOE gene, which has been reported to be associated with COVID-19-positive in the UK Biobank data, was confirmed in Chinese population." (PMID 36531218, 2022). "For this reason, this study may help to provide new avenues for studying ApoE purposes, evaluating not only the effect exerted by ɛ4 but also the protective effect of rs7421 and ɛ2 allele against COVID-19." (PMID 35508522, 2022). "This suggests that APOE ε4 carriers may be more prone to neurological symptoms of COVID-19 than carriers of other alleles." (PMID 35409141, 2022). "Moreover, subjects with the APOE ε4 allele show reduced cerebral blood flow and increased subcortical ischemic white matter damage, all factors that exacerbate COVID-19 symptoms." (PMID 35409141, 2022). "Moreover, we confirmed the association between COVID-19 susceptibility and polymorphisms in the ApoE, ACE1, TMPRSS2, and CCR5 genes." (PMID 35793369, 2022). "In the present study, we investigated the association between the APOE gene polymorphisms and COVID-19 disease severity in the absence of known APOE-related comorbidities in the case group which were risk factors for severe COVID-19." (PMID 35931737, 2022). "Increased viral load may result in increased inflammation and disease severity, as demonstrated by increased frequency of ε4 allele in COVID-19 patients and elevated levels of inflammatory factors in the patients with APOE ε4 genotype." (PMID 35915083, 2022). "However, current evidence points to a greater risk for worse COVID-19 in patients carrying this allele, suggesting an ambiguous effect of APOE." (PMID 35359998, 2022). "Thus, the observed genetic association between APOE alleles and disease severity is in line with in vitro findings and reiterate that APOE e4 allele has a crucial role in COVID-19 severity in patients." (PMID 35931737, 2022). "For example, exploring genetics elements in populations with more homogenous comorbid profiles might offer enhanced precision for studying APOE involvement in COVID-19 risk and prognosis." (PMID 34945790, 2021). "One explanation could be that the APOE e4 genotype (the highest risk factor for AD) has been reported as a predictive factor of severe COVID-19 and death." (PMID 33838684, 2021). "Additionally, APOE ε4ε4 allele was associated with an increased risk of developing severe COVID-19, independently of dementia, and other comorbidities, including cardiovascular disease, and type-2 diabetes." (PMID 33673697, 2021). "They found that APOE-ε4 homozygotes were indeed at increased risk of severe COVID-19 infection and that the association was similar after removing participants with APOE- ε4-associated diseases that were linked also to COVID-19 severity." (PMID 34205498, 2021). "For example, apolipoprotein E (ApoE) e4e4 allele, highly associated with Alzheimer’s, may increase the risk of severe COVID-19." (PMID 34511868, 2021). "Recent studies revealed that ApoE, a protein encoded by APOE gene, may increase the risk of severe COVID-19 cases." (PMID 34179542, 2021). "So, a possible reason for the relation between COVID-19 severity and APOE variants is that APOE∗ε4 might moderate macrophage pro-/anti-inflammatory phenotype in the lungs, which could drive to more extensive tissue damage." (PMID 34179542, 2021). "Recently, a study conducted with the UK Biobank (UKB) community cohort, has revealed that ApoE, specifically the ε4∗ε4 genotype, increases the risk of severe Coronavirus disease 2019 (COVID-19), caused by the severe acute respiratory syndrome coronavirus 2 (SARS-CoV-2)." (PMID 34179542, 2021). "Evaluation of known genetic variants for HDL-cholesterol revealed that individuals homozygous for apolipoprotein E4 alleles had ∼2- to 3-fold higher risk of SARS-CoV-2 infection or mortality from COVID-19 compared with apolipoprotein E3 homozygotes, even after adjustment for HDL-cholesterol levels." (PMID 33667465, 2021).